HLA-B (major histocompatibility complex, class I, B)
Diseases named in the same sentence as HLA-B in open-access papers (continued):
Sharing a sentence is not in itself a finding about the gene and the disease.
Autoimmunity (22 papers, 2009 to 2025). The occurrence of an immune reaction against the organism's own cells or tissues. "Our data confirm that peptides from this region are selectively presented by disease-associated HLA-B alleles, aligning with previous findings on the role of HLA-B∗27–derived peptides in autoimmunity." (PMID 40466865, 2025). "By targeting autoreactive T or B cells, T-cell engagers hold promise for restoring immune tolerance in such conditions as HLA-B*27–associated autoimmunity subtypes, multiple sclerosis, rheumatoid arthritis, and type 1 diabetes mellitus." (PMID 40416957, 2025). "The RRARSVAS peptide is found to strongly bind to the HLA-B*27:05 allele, which is present in 6% of the population, and it seems to be associated with a low risk of autoimmunity." (PMID 38186412, 2023). "Though MDA5 is upregulated in ABC-treated LCL721.221/sHLA-B*57:01, but not in ABC-treated parental LCL721.221 cells, MDA5 function in autoimmunity seems to be associated with the ABC risk allele HLA-B*57:01." (PMID 35055355, 2022). "The patient presented an autoimmunity-associated HLA haplotype (HLA-A*02/HLA-B*08/HLA-C*07/HLA-DRB1*03) and experienced an increase in activated CD8 T-cells along the treatment." (PMID 34200673, 2021). "In conclusion, it is highly likely that more than one of these mechanisms is involved in SpA pathogenesis, and independently or synergistically contributes to the development of autoinflammation or autoimmunity, by exacerbating the pathogenic role of HLA-B*27." (PMID 33092023, 2020). "Risk alleles for HLA-B and HLA-C determine susceptibility to autoimmunity and inflammation." (PMID 38474281, 2024). "While YeiH is present in enteric microbiota and pathogens, additional evidence that pathogenic T cells in HLA-B*27–associated autoimmunity may have had a prior antigenic encounter within the gastrointestinal tract remains lacking." (PMID 39024572, 2024). "It has been demonstrated that HLA-B*57:01 could be susceptible to drug-induced autoimmunity." (PMID 34447375, 2021). "Thus, our finding may in part explain why the HLA-B*27 and HLA-B*57 allele groups are also associated with resolution of other chronic infections (e.g., HCV) and why both HLA-B*27 and HLA-B*57 allele groups are associated with autoimmunity." (PMID 28769934, 2017). "Group B (=low risk of allogenic rejection, low risk for autoimmunity) included 11 T1D islet recipients with one or two HLA DR matches, but mismatched for HLA-DR3 and HLA-DR4 (independently of HLA-A and HLA-B matching)." (PMID 37026004, 2023). "Donor 5443 was unusual, in that this donor was homozygous for a total of 7 out of 9 HLA alleles: HLA-B, HLA-C, HLA-DRB1, DRB4, DQA1, DQB1 and DPA1, with specific HLA alleles more predisposed to autoimmunity." (PMID 36936963, 2023). "Group C (low risk of allogenic rejection, high risk for autoimmunity) included 24 T1D islet recipients with HLA-DR3 and/or HLA-DR4 matches (independently of HLA-A and HLA-B matching)." (PMID 37026004, 2023). "The analysis results suggested that individuals carrying HLA-B*08:01-DRB1*03:01-DQB1*02:01 risk haplotypes were enriched for association with various immune conditions e.g., allergy, asthma, autoimmunity (e.g., SLE, T1D)." (PMID 34976003, 2021). "In the landmark models for the association of HLA-B*35, HLA-DRB1*0701, and HLA-A*02 with RFS or OS, only autoimmunity was found statistically significant (P < .0001)." (PMID 20549830, 2010). "In conclusion, the lack of association between SNPs in the genetic master switches of autoimmunity, PTPN22 and CTLA-4, suggests that regardless of the strong linkage with HLA-B*27, AAU should be regarded as an autoinflammatory rather than an autoimmune condition." (PMID 19180256, 2009).
Autoimmunity (continued). "Interestingly, the pathogenesis of autoimmune/autoinflammatory disorders, such as AS, BD, BSCR and Ps, seems to arise, at least in part, by the epistatic interaction between ERAP1 and a HLA class I molecules (HLA-B*27, HLA-B*51, HLA-A*29:02 and HLA-C*06:02, respectively)." (PMID 33348540, 2020).
influenza (22 papers, 2018 to 2025). An acute viral infection of the respiratory tract, occurring in isolated cases, in epidemics, or in pandemics; it is caused by serologically different strains of viruses (influenzaviruses) designated A, B, and C, has a 3-day incubation period, and usually lasts for 3 to 10 days. "Thus, variants associated with a severe course of influenza were found: HLA-A*11, HLA-B*35, HLA-DRB1*10, and HLA-DRB1*01*01." (PMID 41305516, 2025). "We investigated this by focussing on a known immunogenic HLA‐B*44:03‐restricted influenza‐derived peptide, namely NS1195‐203." (PMID 40980484, 2025). "To investigate the potential presentation of the known HLA‐B*44:03‐restricted influenza‐derived peptide NS1195‐203 across the HLA‐B44 supertype, we first assessed their preferred peptide binding motifs." (PMID 40980484, 2025). "In this study, we investigated the presentation and immunogenicity of a known HLA‐B*44:03‐restricted influenza‐derived peptide NS1195‐203 across the HLA‐B44 supertype." (PMID 40980484, 2025). "As a comparative population, we examined CD8+ T cells specific to the influenza epitope NP.383-391 presented by HLA-B*27 as well as tetramer– CD8+ T cells." (PMID 39024572, 2024). "Due to the use of the pan-class I antibody W6/32 for HLA I isolation, influenza peptides with the capacity to bind HLA-B*35:03 and HLA-C*04:01 were also observed, as well as peptides with predicted capacity to bind more than one of the expressed HLA." (PMID 35255101, 2022). "We observed that influenza immunopeptides were only presented for the secondary length preferences of patient allotypes HLA-A*03:01 and HLA-B*18:01: 10-mers and 8-mers respectively." (PMID 35051231, 2022). "Another example is HLA-B*37:01, HLA-B*18:01 and HLA-B*44:05 (belonging to the HLA-B44 supertype) each able to present the influenza epitope NP338–346 but in distinct conformations due to polymorphisms within the binding cleft." (PMID 34581761, 2021). "Taken together, our data show, that the expression of specific HLAs (like HLA-B*27:05) can lead to immunodomination and markedly reduce immunodominance of universal influenza-specific CD8+ T cells." (PMID 32750095, 2020). "Peptide sequence and thermal stability of HLA-B*18:01 presenting influenza-derived peptides." (PMID 40587260, 2025). "Specifically, influenza samples maintained higher levels of type I IFN response–associated antiviral ISGs (e.g., IFITM1, IFITM2, IFITM3, OAS2, OAS3, OASL) and antigen presentation genes (e.g., HLA-DRB5, HLA-C, B2M, HLA-B, HLA-E)." (PMID 34618691, 2021). "HLA-A*01:01, HLA-A*02:01, HLA-A*03:01, HLA-B*08:01, HLA-B*18:01, HLA-B*27:05, HLA-B*37:01, and HLA-B*57:019–11 are associated with universal protective CD8+ T cell mediated immunity, as they present influenza peptides that were highly conserved over the last century." (PMID 31811120, 2019). "Additionally, during acute influenza infection and chronic HIV progression, viral escape mutations could occur on HLA-B*2705 restricted CD8 T cell epitopes." (PMID 33301503, 2020). "We next probed memory NP338+CD8+ T cell responses in individuals expressing HLA-B*37:01, HLA-B*44:02, HLA-B*44:03, or HLA-B*18:01 by stimulating their peripheral blood mononuclear cells (PBMCs) with a pool of NP338 peptides corresponding to the main variants in the circulating influenza A strains." (PMID 30575715, 2018). "While this was the case for HLA-B, the reverse was observed for HCP5 in humoral immune response to influenza." (PMID 31137555, 2019). "Though the EC50 of SRYWAIRTR peptide binding to HLA-B*27:05 and 06, was not significantly different, the HLA-B*27:06 subtype exhibited a reduced affinity for this influenza derived peptide." (PMID 35958592, 2022).
rheumatoid arthritis (19 papers, 2010 to 2025). A chronic, systemic autoimmune disorder characterized by inflammation in the synovial membranes and articular surfaces. "Previous studies have revealed that Polygonum multiflorum, a well-known herbal medicine that exerts high efficacy in relieving rheumatoid arthritis, is prone to cause approximately liver damage in 45.4% of patients who carry the HLA-B*35:01 allele." (PMID 38467717, 2024). "Previous studies have shown genetic associations of HLA-B in both rheumatoid arthritis and schizophrenia." (PMID 28560257, 2017). "Comparison of frequencies of a subset of HLA-A*, HLA-B* and HLA-DRB1* alleles between patients with rheumatoid arthritis and the Croatian population of bone marrow donors." (PMID 41325321, 2025). "In the case of rheumatoid arthritis (RA), the HLA-DRB1, HLA-A, HLA-B, and HLA-DPB1 genes constitute genetic susceptibility for the development of the disease." (PMID 36981837, 2023). "For example, human susceptibility to rheumatoid arthritis (RA) was found linked strongly with certain MHC class I and II alleles, including HLA-DRB1, HLA-DPB1 and HLA-B." (PMID 31720104, 2019). "HLA-B*27 is the most frequently used genetic marker in rheumatology, according to the five doctors, far ahead of other HLA markers associated to various diseases, such as HLA-DR4 in rheumatoid arthritis, and genes of monogenic diseases (Mediterranean fever or others)." (PMID 26528326, 2015). "Further mechanistic hypotheses enabled by the integration of our HLA-pQTL with HLA-disease data are the effect of HLA-B position 114 DK on the CD1C gene and rheumatoid arthritis." (PMID 39085222, 2024).
uveitis (19 papers, 2011 to 2026). An inflammatory process affecting a part of or the entire uvea. "In SpA, the peripheral articular phenotype appears to be associated with a higher occurrence of uveitis in the presence of HLA-B*51." (PMID 42123313, 2026). "This suggests that the pathogenic mechanisms of B27AAU versus non-HLA-B*27–associated uveitis are distinct, which is supported by distinct genetics associated with B27AAU and HLA-B*27– AAU." (PMID 39024572, 2024). "The HLA-A*29 is strongly associated with Birdshot uveitis in individuals of Western-European ancestry, while HLA-B*27 is associated with uveitis, particularly in ankylosing spondylitis." (PMID 37169817, 2023). "HLA-B27 typing revealed that the incidence of uveitis was associated with the subtypes HLA-B*2704 and HLA-B*2705 [38•, 39, 42]." (PMID 35829981, 2022). "It was also found that A*02:07 is associated with skin lesions and arthritis, A*26:01 with uveitis, and A*30:04 with vascular lesions, genital ulcers, and positive pathergy test, independently of HLA-B*51." (PMID 21429233, 2011). "In particular, HLA-B*39:01, HLA-B*38:01, and HLA-B*08:01 are risk factors for the development of PsA, but HLA-B*27 is associated with more severe forms as well as with specific symptoms, such as spondylitis and uveitis." (PMID 36294757, 2022). "In uveitis, HLA-B*18 and B*35 dominated again (28.0% and 24.0%, respectively), followed by B*08 and B*51 (24.0% each)." (PMID 40806743, 2025). "Specifically, HLA-B*08 and HLA-B*51 were each observed in 24% of patients with uveitis and in 28.57% of those with inflammatory bowel disease." (PMID 40806743, 2025). "A missense mutation in ERAP1 p.Asp725Gln showed susceptibility in patients with BD uveitis only under HLA-B*51 positivity, and ERAP1 susceptibility was abolished in HLA-B*51-negative patients." (PMID 33912164, 2021). "Uveitis is more common in patients with HLA-B*51-positive BD compared with those with HLA-B*51-negative BD." (PMID 33912164, 2021). "The HLA-B*27 is associated with increased risk of AAU, and is a common risk locus for PsA (and other SpA) and uveitis." (PMID 34604268, 2021). "One patient with HLA-B*27:04/B*35:05 had all peripheral manifestations (uveitis, peripheral joint involvement, dactylitis, and enthesitis)." (PMID 33490092, 2020). "PsA patients with both uveitis and axial arthropathy tend to be male and HLA-B*27 positive." (PMID 34604268, 2021). "While both HLA-B*51 and HLA-A*26:01 seemed to be risk factors for uveitis, the risk to uveitis was not escalated with the combination of HLA-B*51 and HLA-A*26:01 than with either one of the two alleles." (PMID 21429233, 2011). "Consequently, we explore the underlying genetics of HLA-B*27 uveitis and distinguish HLA-B*27 positive and HLA-B*27 negative uveitis as two genetically distinct diseases." (PMID 37949852, 2023). "First, we compared the gene expression of 29 ocular CD8+ T cells with the HLA-B*27 axSpA motif in B27AAU to 1,535 expanded ocular CD8+ T cells from other forms of uveitis (non-B27AAU), identifying 76 upregulated DEGs in ocular CD8+ T cells with the HLA-B*27 axSpA motif." (PMID 39024572, 2024).
eosinophilia (18 papers, 2016 to 2025). "Another ADR that is also associated with HLA-B*15:02 and anti-epileptic drugs and HLA-B*58:01 and allopurinol, but also in carbamazepine initiators with HLA-A*31:01 is drug reaction with eosinophilia and systemic symptoms (DRESS)." (PMID 37908589, 2023). "For instance, HLA-B*58:01 is associated with both allopurinol SJS/TEN and drug reaction with eosinophilia and systemic symptoms/drug-induced hypersensitivity syndrome (DRESS/DIHS), however, HLA-B*15:02 is only associated with carbamazepine SJS/TEN." (PMID 37901413, 2023). "HLA-B*13:01 (IMGT/HLA ID: HLA00152) allele has been reported to be associated with dapsone and salazosulfapyridine-induced drug reaction with eosinophilia and systemic symptoms (DRESS)." (PMID 32180714, 2020). "The HLA-B alleles associated with carbamazepine-induced maculopapular exanthema (MPE) and the drug reaction with eosinophilia and systemic symptoms (DRESS) among the Thai population have never been reported." (PMID 29546073, 2018). "The aim of this study was to investigate subsidiary genetic markers that could identify those at further increased risk of developing allopurinol‐induced drug reaction with eosinophilia and systemic symptoms (DRESS) in subjects with HLA‐B*58:01." (PMID 36176736, 2022). "A recent study has concluded that HLA-B*53:01 molecules may be directly or indirectly involved in the mechanisms that induce drug reaction with eosinophilia and systemic symptoms (DRESS) syndrome in patients treated with raltegravir." (PMID 31337377, 2019). "In a Han-Chinese population, a relationship between carbamazepine-induced Maculopapular exanthema (MPE)/Drug Reaction with Eosinophilia and Systemic Symptoms (DRESS) and HLA-B*51:01 (OR 4.56, 95 percent CI 2.0–10.5, p = 0.01) was discovered." (PMID 35450046, 2022).
gout (18 papers, 2014 to 2025). A condition characterized by painful swelling of the joints, which is caused by deposition of urate crystals. "How do host genetics (e.g., ABCG2 polymorphisms, HLA-B*5801) interact with microbiota composition to modify gout susceptibility and severity?" (PMID 41583434, 2025). "For the first time in Vietnam, we report the frequency of the HLA-B*58:01 allele in a randomly selected gout patient group living in the northeastern region." (PMID 40870966, 2025). "Allopurinol remains the first-line treatment for gout; however, it carries a risk of severe cutaneous adverse reactions (SCARs), particularly among carriers of the HLA-B*58:01 allele." (PMID 40844324, 2025). "The genotype and frequencies of the HLA-B*58:01 allele observed in this Vietnamese cohort of gout patients are consistent with data reported in Vietnam." (PMID 40870966, 2025). "The results demonstrated that the frequency of the single HLA-B*58:01 allele in Vietnamese patients with gout with ALP-induced MCARs was the highest (38.1%; 8 of 21)." (PMID 34573954, 2021). "A previous study in a Han Chinese population showed that 100% of ALP-treated patients with gout and MCARs carry the HLA-B*58:01 allele." (PMID 34573954, 2021). "In this study, we found that gout risk remained higher in Taiwanese men compared to women, after HLA-B genetic variants were included in the model." (PMID 30934611, 2019). "Using Taiwan Biobank and the National Health Insurance Research Database (NHIRD), we examined hyperlipidemia, sex, and their relationship with gout among Taiwanese adults with the human leukocyte antigen B (HLA-B) genetic variants." (PMID 30934611, 2019). "After stratification by sex and HLA-B variants of interest, we found that hyperlipidemia remained a significant risk factor for gout, with a higher odds ratio found in women." (PMID 30934611, 2019). "Further investigation is necessary to clarify the possible mechanisms through which the interaction between sex and hyperlipidemia on gout risk is modulated by these single nucleotide polymorphisms (SNPs) in HLA-B gene." (PMID 30934611, 2019). "In the present study, we found that 16.33% of Thai people carry the HLA-B*58:01 allele, which is associated with allopurinol hypersensitivity in gout treatment." (PMID 25657656, 2014). "Additionally, HLA-B*13:02 has been associated with allopurinol (a medication used to treat gout and hyperuricemia)-induced DRESS in the Shanghai population." (PMID 39464636, 2024). "Therefore, according to ACR 2020 gout guidelines, testing for the HLA–B*5801 allele prior to starting allopurinol is recommended for patients of Southeast Asian descent and for African American patients." (PMID 35566594, 2022). "Moreover, we also revealed that besides the HLA-B*58:01 allele, several other alleles, such as HLA-A*33:03, HLA-A*24:02, HLA-B*58:01, HLA-A*02:01 and HLA-A*29:01, also appeared in patients with gout at a high frequency." (PMID 34573954, 2021). "Therefore, the aim of this study was to investigate the associations of gout with hyperlipidemia and sex among carriers of HLA-B gene variants (rs2523608 and rs4713518) in Taiwan." (PMID 30934611, 2019). "However, another study on Kinh Vietnamese reported that only approximately 6.8% of a total of 75 patients with gout and MCARs were positive for the HLA-B*58:01 allele, a frequency that is almost equal to that observed in healthy Kinh Vietnamese individuals (6.5%)." (PMID 34573954, 2021). "In addition to the presence of the HLA-B*58:01 allele, one-locus haplotypes of HLA-A*02:01/HLA-A*24:02 and HLA-A*02:01/HLA-A*29:01 probably play an important role in the occurrence of ADRs with mild symptoms in patients with gout treated with ALP." (PMID 34573954, 2021). "Interestingly in our findings, we found that there was an interaction between hyperlipidemia and sex on gout risk among specific HLA-B genotypes, even though the mechanism of such an association remains unclear." (PMID 30934611, 2019).